MPO (myeloperoxidase)
Diseases named in the same sentence as MPO in open-access papers (continued):
Sharing a sentence is not in itself a finding about the gene and the disease.
Airway obstruction (5 papers, 2017 to 2025). Obstruction of conducting airways of the lung. "For example, the mucus plugs in the airways of patients with COPD increase, and the level of MPO/NETs complex in mucus plugs is negatively correlated with the patients’ lung function, indicating that the extensive formation of NETs leads to airway obstruction." (PMID 35346147, 2022). "Activated neutrophils secrete MPO which then induces oxidative stress, thereby resulting in oxidative damage of respiratory cells, lung inflammation, cytotoxicity, airway obstruction, and decrease of lung function." (PMID 28659663, 2017). "Neutrophil elastase stimulates mucin production and secretion, leading to mucus hypersecretion and airway obstruction, whereas MPO promotes oxidative tissue damage and initiates alterations in cellular homeostasis, and increases the response of lung epithelial cells to proinflammatory stimuli." (PMID 39854548, 2025). "Neutrophil elastase can stimulate the production and secretion of mucin, leading to excessive mucus secretion and airway obstruction, while MPO can promote oxidative tissue damage and initiate cell homeostasis changes, and increase the response of lung epithelial cells to pro-inflammatory stimuli." (PMID 38076255, 2023).
allergic asthma (5 papers, 2011 to 2022). A asthma with a basis in a pathological type I hypersensitivity reaction. "A significant increase of MPO was also demonstrated in patients with allergic asthma." (PMID 21255397, 2011). "However, the role of MPO in allergic asthma is yet to be studied." (PMID 34692717, 2021). "Carbamylated proteins were detected in atherosclerotic plaques adjacent to MPO, in dysfunctional HDL induced by MPO, and at inflammatory sites of eosinophil-driven allergic asthma." (PMID 35624754, 2022).
allergic disease (5 papers, 2014 to 2025). An immune response that occurs following re-exposure to an innocuous antigen, and that requires the presence of existing antibodies against that antigen. "Children with higher value of Growth Arrest and DNA Damage Inducible-α (GADD45A) as well as the proteases MPO and MMP9 also had higher risk to develop allergy." (PMID 33722194, 2021). "The granule enzyme MPO, that is restricted to neutrophils and monocytes, also appeared to be predictive of allergy development." (PMID 33722194, 2021). "Neutrophils are known to have a crucial function in the allergy-mediated inflammatory response, for instance by release of proteases, myeloperoxidase (MPO) or elastase." (PMID 24466205, 2014). "Similarly, the MPO activity (marker of neutrophil infiltration) raised significantly during the inflammation and allergy." (PMID 34452623, 2021).
aortic valve stenosis (5 papers, 2016 to 2024). Aortic valve stenosis (AVS) is a condition characterized by narrowing of the heart's aortic valve opening. "We obtained a result showing statistically significantly higher plasma myeloperoxidase levels in patients with aortic valve stenosis compared to the control group (p < 0.00003)." (PMID 31362438, 2019). "MPO levels were determined in the control group and in the patients with aortic valve stenosis in all three severity grades of the aortic valve stenosis." (PMID 31362438, 2019). "The results showed that myeloperoxidase levels increased with the increase in the severity of the aortic valve stenosis and that they reached the highest level in the patient group with severe stenosis." (PMID 31362438, 2019). "In this case report, a 74-year-old woman was diagnosed as having myeloperoxidase (MPO)-ANCA-positive GD with severe aortic valve stenosis (AS)." (PMID 27654701, 2016). "In this case report, we describe the outcomes after aortic valve replacement (AVR) for severe aortic valve stenosis (AS) in a 74-year-old woman with MPO-ANCA-positive GD." (PMID 27654701, 2016). "For example, pharmacological inhibition of MPO via AZM198 prevents plaque stability in a murine model of Tandem Stenosis, while the same MPO inhibitor stabilises atherosclerotic plaques in pre-existing atherosclerotic plaques in various substrate inhibitors mitigating the course of disease." (PMID 38673843, 2024). "Logistic regression analysis for aortic valve stenosis in MPO-AAV patients." (PMID 33481903, 2021). "Recent findings show that MPO is highly expressed in the aortic valve stenosis (AS) patients." (PMID 34440245, 2021).
arteriosclerosis (5 papers, 2020 to 2022). A vascular disorder characterized by thickening and hardening of the walls of the arteries. "High levels of MPO exacerbate arteriosclerosis and promote disease progression." (PMID 35529262, 2022). "This may be caused by the lack of an increase of HMGB1 in surgical patients while MPO plasma release underlies a high number of influencing factors, such as arteriosclerosis as well as systemic heparin-application, which is highly prevalent in severely ill and cardiac surgical patients." (PMID 31936385, 2020).
bladder cancer (5 papers, 2013 to 2025). "The variant genotypes of MPO may be related to low enzyme activity and polymorphisms in MPO that was related to a decreased risk of bladder cancer developing in Tunisian population." (PMID 38530585, 2024). "Our findings also highlight the potential role of MPO in bladder cancer, as its expression correlated with oligomannose-rich glycosylation and was predominantly localized to the immune component of the tumor microenvironment." (PMID 40430030, 2025). "Based on both peptide-spectra matches (PSMs) and glycoPSMs, MPO emerged as the most abundant glycoprotein, particularly in more aggressive stages of bladder cancer (T1 and MIBC)." (PMID 40430030, 2025). "These insights are consistent with our findings and support a plausible role for MPO glycosylation in immune modulation, though direct demonstration in the context of bladder cancer is still required." (PMID 40430030, 2025). "This study highlights the potential of the CUBN/MPO ratio as a prognostic biomarker for high-grade T1 bladder cancer." (PMID 38530585, 2024). "In contrast, this paper investigates a specific biomarker, the CUBN/MPO ratio, in high-grade T1 bladder cancer." (PMID 38530585, 2024). "This study aimed to investigate the potential of the cubilin/myeloperoxidase (CUBN/MPO) ratio as a high-grade T1 bladder cancer biomarker." (PMID 38530585, 2024). "Further, IF staining of tumor tissue arrays from 782 patients with breast, lung and bladder cancer revealed two distinct populations: CitH3+MPO+ and CitH3+HMGB3+." (PMID 36973439, 2023). "Our results suggest that low CUBN/MPO ratio could be a biomarker to select aggressive high-grade T1 bladder cancer patients to be candidates to early cystectomy and improve their oncologic outcome; however, a prospective trial will be necessary." (PMID 38530585, 2024). "However, despite these limitations, these results must be considered as a preliminary work and further work should be conducted to evaluate and validate the role of CUBN/MPO ratio and to find the biological mechanisms underlying the relationship between CUBN and MPO in high-grade T1 bladder cancer." (PMID 38530585, 2024). "The reduced expression of this enzyme likely demonstrates that the accumulation of oligomannose structures on MPO in bladder cancer derives from complete processing in the ER, without the participation of the alternative pathway involving MANEA." (PMID 40430030, 2025).
candidiasis (5 papers, 2013 to 2024). Infection with the organism Candida. "A relatively common genetic condition that predisposes patients to invasive candidiasis is myeloperoxidase (MPO) deficiency." (PMID 32185141, 2020). "Patients with MPO deficiency are narrowly susceptible to Candida spp.; still, only a small fraction of patients ever develop invasive candidiasis." (PMID 32185141, 2020).
celiac disease (5 papers, 2020 to 2023). An autoimmune genetic disorder with an unknown pattern of inheritance that primarily affects the digestive tract. "Clinical manifestations and double positivity for both myeloperoxidase (MPO) and anti-proteinase 3 (PR3) antibodies argued against the fact that that these findings were secondary to vaccination, cocaine abuse, or celiac disease." (PMID 35630067, 2022). "Myeloperoxidase (MPO) activity, adenosine deaminase, nitric oxide (NOx), thiobarbituric acid, catalase (CAT), superoxide dismutase (SOD), glutathione peroxidase (GPx), and DNA damage were evaluated in peripheral blood samples from 47 celiac disease patients and 31 controls." (PMID 32555942, 2020).
cervical cancer (5 papers, 2018 to 2024). A primary or metastatic malignant neoplasm involving the cervix. "On the plus side, MPO can protect against cancers associated with serious infections, such as cervical cancer." (PMID 38275657, 2024). "Women with the GG polymorphism in promoter region of the myeloperoxidase gene G463A have been reported to produce more myeloperoxidase and have a lower possibility of developing cervical cancer than those who have the heterozygous genotype GA24." (PMID 30206371, 2018). "In a clinical study with 100 invasive cervical cancer patients and 122 healthy controls, the GG genotype was protective against cancer compared with the GA genotype, possibly due to the role of MPO oxidation products in killing HPV-transformed cells." (PMID 38275657, 2024). "Here, we observed two molecular markers of chronic inflammation, MPO and nitrotyrosine, which were significantly changed in the cervical fluid of the females with cervical cancer (CIN III)." (PMID 36230630, 2022). "Finally, stromal CD66b+ neutrophils and myeloperoxidase/citrullinated histone H3 (MPO/H3Cit)-labeled neutrophil extracellular trap (NETs) have been recently identified as an independent prognostic factor for recurrence-free survival (RFS) in cervical cancer." (PMID 38529474, 2024). "Functional annotation was performed using GO analysis on 1,056 differently expressed proteins to identify those that may impact cervical cancer, such as heme protein myeloperoxidase, which is involved in the immune process, and APOA1, which is associated with lipid metabolism." (PMID 33194326, 2020).
chronic bronchitis (5 papers, 2011 to 2024). A type of chronic obstructive pulmonary disease characterized by chronic inflammation in the bronchial tree that results in edema, mucus production, obstruction, and reduced airflow to and from the lung alveoli. "There were significant increases in IL-8, myeloperoxidase (MPO), and HA in the BAL fluid of chronic bronchitis patients." (PMID 35625586, 2022). "COPD patients with chronic bronchitis had a similar number of neutrophils and MPO-positive cells when compared with COPD patients without chronic bronchitis (not shown)." (PMID 22140545, 2011). "A bronchoscopic study of 42 subjects with chronic bronchitis (with and without airflow obstruction) and 13 healthy controls found increased activity of CXCL8, myeloperoxidase, hyaluronan, and eosinophil cationic protein." (PMID 26424214, 2015).
coronary stenosis (5 papers, 2015 to 2023). Narrowing of the coronary artery lumen diameter. "Plasma nucleosome levels were also observed to be associated with an increased risk of coronary stenosis, and the presence of MPO-DNA complexes supports a close link with the occurrence of major adverse cardiac events." (PMID 36672621, 2023). "The increase of plasma MPO level was associated with both the occurrence of CAD and the severity of coronary artery stenosis in diabetic patients." (PMID 26451069, 2015). "The Gensini score, which was served to assess the degree of coronary stenosis, increased progressively along with the increasing plasma MPO level." (PMID 26451069, 2015). "At the same time, MPO was correlated with the degree of coronary artery stenosis." (PMID 35419382, 2022).
cystitis (5 papers, 2013 to 2023). Inflammation of the urinary bladder. "Rat models of cystitis typically display thickening of the bladder epithelial layer, increased MPO activity, and the induction of proinflammatory cytokines." (PMID 37463180, 2023). "The MPO net activity, for instance, was much lower than reported in acute cystitis models, thus suggesting a scarce neutrophil granulocyte infiltration." (PMID 38249555, 2023). "Previously, we measured tissue concentrations of myeloperoxidase (MPO) to determine the level of cystitis." (PMID 24204996, 2013). "The massive migration of neutrophils is also a feature of cystitis induced by CYP administration, as indicated by the increase of MPO activity in the bladder tissue when compared to that of the saline group." (PMID 26154141, 2015).
epilepsy (5 papers, 2020 to 2025). A brain disorder characterized by episodes of abnormally increased neuronal discharge resulting in transient episodes of sensory or motor neurological dysfunction, or psychic dysfunction. "Animal and molecular experiments confirmed that acute alcohol exposure increases the susceptibility to epileptic seizures, whereas the MPO inhibitor 4-aminobenzoic acid hydrazide showed therapeutic potential for alcohol-induced epilepsy." (PMID 41674657, 2025). "Apigenin abrogates the myeloperoxidase-induced oxidative damage in the kainic acid-induced model of epilepsy." (PMID 35630774, 2022). "The production of hypochlorite (HClO) by myeloperoxidase is contemplated to be closely related to the development of epilepsy." (PMID 35630774, 2022). "On top of that, the myeloperoxidase (MPO) activity is an indicator of neutrophil infiltration and inflammatory cytokine activation in the FeCl3 injection-induced epilepsy animal model." (PMID 36118077, 2022).
experimental autoimmune encephalomyelitis (5 papers, 2020 to 2025). An autoimmune demyelinating disease of the central nervous system that is produced experimentally in animals by the injection of homogenized brain or spinal cord in Freund's adjuvant. "It will be important to test if MPO−/− neutrophils have the same capacity to migrate across endothelial barriers in vitro and in disease models such as experimental autoimmune encephalomyelitis." (PMID 35453292, 2022). "Treatment of MPO inhibitor KYC restored the BBB function in experimental autoimmune encephalomyelitis mice, showing its potential to prevent inflammatory factors-mediated BBB damage." (PMID 32508671, 2020).
granulocytic sarcoma (5 papers, 2010 to 2025). A tumor mass composed of myeloblasts, neutrophils and neutrophil precursors. "Cervical biopsy showed granulocytic sarcoma, with positive staining for MPO, CD117, CD99, CD34, and CD68 (partial), and negative staining for CD20, CD79a, CD10, CD3, CD56, CD138, desmin, CK, myogenin, EMA, and cyclin D1." (PMID 35713448, 2022). "Granulocytic sarcoma is a collection of granulocytic precursor cells, named chloroma for its greenish appearance under the skin due to presence of myeloperoxidase." (PMID 29147181, 2010). "Immunohistochemical staining showed strong positivity for myeloperoxidase (MPO), lysozyme, and CD68, with weak scattered staining for CD3, CD5, and CD20, confirming granulocytic sarcoma." (PMID 40951125, 2025). "Myeloperoxidase and PBO were strongly positive, and diagnosis of granulocytic sarcoma was confirmed." (PMID 24093066, 2013).
hepatocellular carcinoma (5 papers, 2012 to 2024). A malignant tumor that arises from hepatocytes. "We also observed increased immune cell myeloperoxidase (MPO) activity in liver samples with steatohepatitis and hepatocellular carcinoma." (PMID 39959811, 2024). "Moreover, high and sustained MPO activity results in oxidative DNA damage, which is associated with the ultimate and most devastating complication of NASH, hepatocellular carcinoma." (PMID 23285030, 2012).
idiopathic interstitial pneumonia (5 papers, 2018 to 2023). A class of diffuse lung diseases that typically affect the pulmonary interstitium, although some also have a component affecting the airways (for instance, Cryptogenic organizing pneumonitis). "Fifty-eight consecutive patients firstly referred for idiopathic interstitial pneumonia and showing serological positivity of anti-MPO antibodies were retrospectively enrolled." (PMID 34207641, 2021). "The role of anti-MPO antibodies in patients with idiopathic interstitial pneumonia (IIPs) remains unclear." (PMID 34207641, 2021). "In particular, anti-MPO antibodies have been reported in 4–36% of patients with idiopathic interstitial pneumonia, including IPF, while the occurrence of MPA has been described in a range from 1.7 to 25.7% of patients." (PMID 34207641, 2021).
Immunodeficiency (5 papers, 2016 to 2025). Failure of the immune system to protect the body adequately from infection, due to the absence or insufficiency of some component process or substance. "MPO is beneficial for host defense, and a deficiency in MPO results in immune deficiency." (PMID 36979896, 2023). "The difference in the degree of immunodeficiency between CGD and MPO-deficient patients has suggested that MPO-derived oxidants are not as essential as the upstream oxidants." (PMID 35945238, 2022).
iron deficiency (5 papers, 2015 to 2024). "The adverse effects of iron deficiency encompass diminished intracellular bactericidal activity of neutrophils due to decreased myeloperoxidase activity." (PMID 39770983, 2024). "Iron deficiency has been associated with impaired cytokine activity and immune cell proliferation and decreased activity of myeloperoxidase, an iron-dependent enzyme in neutrophils responsible for killing bacteria." (PMID 27387046, 2016). "Hematologic malignancies, common cancers, cytotoxic agents, some antiinflammatory drugs, iron deficiency, lead intoxication, thrombotic conditions, renal transplantation, serious infections, neuronal lipofuscinosis, pregnancy and DM have been shown among the causes of acquired MPO deficiency." (PMID 26719776, 2015).
keratitis (5 papers, 2014 to 2022). A corneal disease that is characterized by inflammation of the cornea. "In the present study, a test for myeloperoxidase (MPO) protein was used to detect infiltrating neutrophils over the short time course of an Aspergillus fumigatus-induced keratitis model." (PMID 25464008, 2014). "In vitro investigations showed that 4E1RCat also halted the decrease in interleukin-1β production, myeloperoxidase levels, and neutrophil recruitment in murine Aspergillus fumigatus keratitis by means of inhibiting eIF4E/4E-BP1 binding, as well as stopping the increase in fungal load and apoptosis." (PMID 33802476, 2021).
leukocytoclastic vasculitis (5 papers, 2022 to 2025). "Histopathologic analysis of a skin biopsy revealed leukocytoclastic vasculitis, and serological testing showed borderline MPO-ANCA positivity." (PMID 41523444, 2025). "Biopsy of skin lesions showed leukocytoclastic vasculitis, and serologic testing yielded borderline myeloperoxidase-specific antineutrophil cytoplasmic antibody (MPO-ANCA) positivity." (PMID 41523444, 2025). "MPO-ANCA activates neutrophils, leading to endothelial injury and leukocytoclastic vasculitis." (PMID 41179045, 2025). "In addition, the patient had very high serum MPO-ANCA levels (> 300 IU/mL) and leukocytoclastic vasculitis in the skin, leading to the suspicion of an overlap with AAV." (PMID 35025058, 2022). "In addition, the patient had a high serum MPO-ANCA level and leukocytoclastic vasculitis in the skin; hence, SLE/AAV overlap syndrome was suspected." (PMID 35025058, 2022).